ENSG00000200620
Synonyms: LOC124905268
Gene: Small nucleolar RNA gene on chromosome X (15,716,208 to 15,716,346, forward strand). Ensembl gene ENSG00000200620.
Gene Ontology:
Biological process: RNA processing
Cellular component: nucleolus
Homologues: Orthologues: rat LOC120095420 (81% identical), mouse Gm54983 (67% identical). Paralogues in human: SNORA7A (86% identical), SNORA7B (86% identical).